MIR320B1 (microRNA 320b-1)
Synonyms: hsa-mir-320b-1; MIR320B-1; MIRN320B1; mir-320b-1
Gene: MicroRNA gene on chromosome 1 (116,671,749 to 116,671,827, forward strand). Ensembl gene ENSG00000211543.
Gene Ontology:
Biological process: cellular response to glucose stimulus; long-term synaptic potentiation; miRNA-mediated post-transcriptional gene silencing; negative regulation of gene expression; positive regulation of stem cell proliferation
Cellular component: RISC complex
Homologues: Orthologues: chimpanzee ptr-mir-320b-1 (100% identical), tropical clawed frog xtr-mir-320 (41% identical). Paralogues in human: MIR320B2 (65% identical), MIR320A (63% identical), MIR320C2 (54% identical), MIR320E (54% identical), MIR320D2 (52% identical).